IL12B (interleukin 12B)
Diseases named in the same sentence as IL12B in open-access papers (continued):
Sharing a sentence is not in itself a finding about the gene and the disease.
cervical cancer (6 papers, 2015 to 2024). A primary or metastatic malignant neoplasm involving the cervix. "Epidemiological studies have shown that IL-12B is associated with an increased incidence of cervical cancer." (PMID 38714987, 2024). "By electronic and manual searches concerning the association of IL-12B rs3212227 and IL-6 rs1800795 polymorphisms and cervical cancer risk, 297 relevant studies up to November 05, 2019 were identified." (PMID 32458622, 2020). "Primary studies have shown that the IL-12B rs3212227 and IL-6 rs1800795 polymorphisms are associated with an increased risk of cervical cancer." (PMID 32458622, 2020). "Stratified analysis by ethnicity revealed that both IL-12B rs3212227 and IL-6 rs1800795 polymorphisms were associated with risk of cervical cancer in Asian women." (PMID 32458622, 2020). "Some epidemiological studies suggested that IL-12B rs3212227 and IL-6 rs1800795 polymorphisms are associated with an increased risk of cervical cancer." (PMID 32458622, 2020). "And, a previous study reported that the loci of rs3212227 in IL-12B gene definitely contributed to increasing cervical cancer risk in Chinese population." (PMID 28415696, 2017). "In addition, more meta-analyses have shown that potentially functional polymorphisms of IL12A and IL12B are thought to increase the risk of malignancies such as gastric, lung, and cervical cancers." (PMID 36950684, 2023). "Our pooled data revealed that the IL-12B rs3212227 and IL-6 rs1800795 polymorphisms may be used to identify individuals at high risk of cervical cancer in Asian women." (PMID 32458622, 2020). "In summary, our pooled data revealed that IL-12B rs3212227 and IL-6 rs1800795 polymorphisms could be used to identify individuals at high risk of cervical cancer in Asian women." (PMID 32458622, 2020). "However, our subgroup analysis revealed that IL-12B rs3212227 polymorphism was significantly associated with risk of cervical cancer in Asians." (PMID 32458622, 2020). "Thus, we systematically reviewed previous publications and a meta-analysis was conducted to evaluate the associations of IL-12B rs3212227 and IL-6 rs1800795 polymorphisms with risk of cervical cancer." (PMID 32458622, 2020). "However, subgroup analysis by ethnicity showed a significant association between IL-12B rs3212227 polymorphism and an increased risk of cervical cancer in Asian women (CA vs. AA: OR = 1.349, 95% CI 1.032-1.762, p=0.028 and CC+CA vs. AA: OR = 1.340, 95% CI 1.041-1.725, p =0.023)." (PMID 32458622, 2020). "In this meta-analysis, we explore the role of XRCC3 rs861539, MTHFR rs1801133, IL-6 rs1800795, IL-12B rs3212227, TNF-α rs1800629, and TLR9 rs352140 polymorphisms in susceptibility to cervical cancer." (PMID 34837895, 2021). "We performed this meta-analysis to explore the role of XRCC3 rs861539, MTHFR rs1801133, IL-6 rs1800795, IL-12B rs3212227, TNF-α rs1800629 and TLR9 rs352140 polymorphism with susceptibility to cervical carcinoma." (PMID 34837895, 2021). "In this meta-analysis, the association of XRCC3 rs861539, MTHFR rs1801133, IL-6 rs1800795, IL-12B rs3212227, TNF-α rs1800629 and TLR9 rs352140 polymorphisms with susceptibility to cervical carcinoma was assessed by including all relevant studies." (PMID 34837895, 2021). "In another example, the mutation of IL-12B rs3212227 disrupts immune regulation in the host, leads to persistent HPV infection and promotes the occurrence of cervical cancer." (PMID 25928231, 2015). "The pooled analysis showed that XRCC3 RS861539, TNF-α rs1800629, and IL-6 rs1800795 were associated with cervical carcinoma susceptibility, but not MTHFR rs1801133, IL-12B rs3212227 and TLR9 rs352140 polymorphisms." (PMID 34837895, 2021).
glioma (6 papers, 2021 to 2025). A benign or malignant brain and spinal cord tumor that arises from glial cells (astrocytes, oligodendrocytes, ependymal cells). "Amplified IL-12A and IL-12B gene expression profiles were also observed in human high-grade glioma samples compared to the controls." (PMID 41034696, 2025). "Results demonstrated that, when cocultured with DHX9‐overexpressed glioma cells, macrophages exhibited decreased expression of M1 markers (IL‐1b, IL‐12b, and TNF‐α) and increased expression of M2 markers (IL‐10, CD163, and ARG1)." (PMID 36377508, 2023). "Indeed, in a human glioma (de novo and recurrent) scRNA-seq dataset, we found that IL12B was mainly expressed in the DC cluster." (PMID 40842154, 2025). "Protective genetic changes in glioma include increased expression of ADGRB3/1, IL12B, DYRKA1, VEGFC, LRRC4, and BMP4." (PMID 39022728, 2024). "We identified 8 plasma proteins which were increased in gliomas vs. meningiomas (GFAP, NEFL, EDDM3B, PROK1, MMP3, CTRL, GP2, SPINT3) and 4 proteins which were decreased in gliomas vs. meningiomas (FABP4, ALDH3A1, IL-12B and OXT)." (PMID 36959545, 2023). "The data shown in our study indicate that overexpressed JMJD1C increases the expression of M1 markers (IL‐1β, TNF, CXCL9, IL‐23, ROS1, IL‐12a, and IL‐12b) both in the glioma mouse models and in the CD14+ monocytes co‐cultured with glioma cells." (PMID 34586733, 2021).
malaria (6 papers, 2009 to 2018). Malaria is a serious and sometimes fatal disease caused by a parasite that commonly infects a certain type of mosquito which feeds on humans. "The GC allele of host IL-12b rs17860508 was associated with a high risk of clinical malaria occurrence compared to the TTAGAG allele (TTAGAG vs TTAGAG/GC, p = 0.004; TTAGAG vs GC, p = 0.002)." (PMID 30022038, 2018). "Both homozygous alleles of TT and GC in IL-12b rs2288831 and rs17860508 were related to increased incidence of developing clinical malaria, compared to the homozygous alleles of CC and TTAGAG respectively." (PMID 30022038, 2018). "A strong linkage was identified amongst IL-12b gene SNP rs2546890, rs2288831 and rs17860508, and the association of haplotypes with malaria episodes was subsequently investigated." (PMID 30022038, 2018). "IL12B+1188 polymorphism showed strong genetic association with the blood parasite level in the malaria patients both at genotype and allele levels." (PMID 23071570, 2012). "Critical role of IL12B in malaria has been demonstrated by other studies that show IL12 production is inversely associated with disease severity in human malaria and the molecule is extremely effective in correcting malarial anemia in murine model." (PMID 23071570, 2012). "Presence of IL12B+1188 polymorphism in five of six multifactor models reinforced its strong genetic impact on malaria phenotype." (PMID 23071570, 2012). "The unequal expression of IL12B between marker genotypes and allelic imbalance detected in malaria patients' PBMC samples strongly suggest that IL12B+1188 polymorphism executes a cis-regulatory function." (PMID 23071570, 2012). "Genotype and allele frequencies of the IL12B promoter polymorphism in Thai malaria patients." (PMID 20003322, 2009). "The allele specific expression of IL12B in the peripheral blood mononuclear cells (PBMCs) of malaria patients by 3′UTR polymorphism may be attributed to (i) differential transcript stability, (ii) influence of microRNAs and (iii) conformational change in RNA secondary structure." (PMID 23071570, 2012). "The presence of IL12B+1188 in five of six models and elevation of odds ratio of TLR4Thr399Ile, TNF-1031 and LTA80 in combination with IL12B+1188 are suggestive of a pivotal genetic influence of IL12B on malaria phenotype." (PMID 23071570, 2012). "We have collated the genetic data on IL12B from the present report with that on toll-like receptors and cytokine loci from our previous study to model the possible genetic interactions that may account for the differences in blood parasitemia in malaria patients." (PMID 23071570, 2012).
psoriatic arthritis (6 papers, 2008 to 2025). Joint inflammation associated with psoriasis. "Previous research by Weronica E and others investigated the causal effects of inflammatory proteins on inflammatory diseases and found that IL12B has a protective effect in psoriatic arthritis." (PMID 39932908, 2025). "On the other hand, polymorphisms in IL23R, TNFAIP3, PTPN22 (tyrosine-protein phosphatase non-receptor type 22), IL12B, RUNX1 (CD8-lymphocyte activation and differentiation), IL13, KIR (killer-cell immunoglobulin-like receptor), and MAGI1 genes have shown association with psoriatic arthritis." (PMID 37628670, 2023).
Salmonella Infections (6 papers, 2014 to 2025). Infections with bacteria of the genus SALMONELLA. "Nonetheless, in patients with IL12B mutations with milder phenotype, the need for a prophylactic antibiotic is debated and may be restored for those with recurrent Salmonella infection." (PMID 35232430, 2022). "In conclusion, cutaneous vasculitis in MSMD patients could be pathognomic of an underlying IL12B or IL12Rβ1 deficiency, particularly in those complicated with Salmonella infections." (PMID 34389021, 2021). "Only IL12B, encoding a key regulator of Th1 polarization, and the antimicrobial peptide genes AVBD2 and AVBD6 were modulated 20 days after Salmonella infection." (PMID 40079593, 2025). "Activation of IL12b:IL18➔ IFN-γ axis is one of most important mechanisms in the fight against Salmonella infection." (PMID 25162711, 2014). "Individuals with inherited or acquired defects in TH1 immunity, such as those with IFNγ/IL12B/IFNγR1 polymorphisms or HIV/AIDS, are more susceptible to nontyphoidal Salmonella infections, but not to enteric fever." (PMID 38497655, 2024). "Only one patient, PID04, presented with recurrent Salmonella infection, which is a common MSMD presentation associated with mutations in IL12RB1 and IL12B, however, no plausible disease-causing variants in either of these genes were identified in this patient through WES." (PMID 34517836, 2021).
type 1 diabetes (6 papers, 2007 to 2025). "This is reminiscent of the 3’UTR SNP in the IL12B gene which affects gene expression and is associated with susceptibility to type 1 diabetes and other diseases in humans." (PMID 33228033, 2020). "Therefore, we investigated the contribution of IL12B to type 1 diabetes susceptibility, as thoroughly as possible, by genotyping a SNP (A1159C; rs3212227), two rare nsSNPs (rs3213096 and rs3213119), a microsatellite (D5S2941) and a set of tag SNPs for the IL12B region." (PMID 18045485, 2007). "M55V substitution results in a 5.5-fold increase in NF-κB transcription, while the expression of IL-12B is trebled, which consequently lead to an autoimmune response and Type 1 Diabetes (T1D)." (PMID 34956330, 2021). "In human type 1 diabetes (TIDM), the genetic susceptibility locus, IDDM18, is located near a regulatory allele of the IL-12 p40 gene (IL-12B), and single nucleotide polymorphisms in this region associate with an earlier age of T1DM onset and accelerated deterioration in glycemic control." (PMID 26555476, 2015). "To investigate the possibility of a polymorphism associated with type 1 diabetes in IL12B that we, or others, have not yet genotyped, we adopted an linkage disequilibrium (LD) mapping approach using tag SNPs." (PMID 18045485, 2007). "IL12B has been reported to be associated with type 1 diabetes in some but not all studies." (PMID 18045485, 2007). "We did not obtain any evidence of an association between type 1 diabetes and either ICAM1, IL12B or TBX21, all of which had previously been associated with type 1 diabetes." (PMID 18045485, 2007).
viral infection (6 papers, 2019 to 2025). "In the transcriptome data, Il1b and Ptgs2 (encoding cyclooxygenase 2, COX‐2) showed higher elevation at almost all the time points post viral infection, while some other genes like Il6, Il12b, and Cxcl5 only showed significant elevation at 48 hpi." (PMID 38992966, 2025). "To test whether these protein candidates would be detectable in clinical samples, we selected four proteins (IL1Α, IL12B, DEFB4A, and CAMP) for ELISA analysis based on the following criteria: abundance, repeatability, and association with viral infection." (PMID 32867704, 2020). "Furthermore, IL1A, IL12B, DEFB4A, and CAMP, which are associated with the inflammatory response and inhibition of viral infection, were significantly more abundant in the HSV-1 epithelial keratitis patients than in the healthy control subjects." (PMID 32867704, 2020).
pulmonary fibrosis (5 papers, 2013 to 2021). Chronic progressive interstitial lung disorder characterized by the replacement of the lung tissue by connective tissue, leading to progressive dyspnea, respiratory failure, or right heart failure. "Furthermore, consistently unique cytokine expression patterns of regenerative and growth factors (CCL2, CCL11, IL6, IL12B, and CXCL8) may indicate activation of pulmonary fibrosis signaling pathways after aberrant inflammatory response." (PMID 35145507, 2021).
systemic lupus erythematosus (5 papers, 2012 to 2025). An autoimmune multi-organ disease typically associated with vasculopathy and autoantibody production. "IL-12B gene has been implicated in the pathogenesis of a multitude of diverse autoimmune diseases, such as Psoriasis, Systemic lupus erythematosus (SLE), Crohn’s disease (CD) and Ulcerative colitis (UC)." (PMID 26103568, 2015).
tuberculosis (5 papers, 2010 to 2025). A chronic, recurrent infection caused by the bacterium Mycobacterium tuberculosis. "A haplotype in interleukin 12B was nominally associated with tuberculosis (p = 0.02), but after permutation testing, done to assess the significance for the entire analysis, this was not globally significant." (PMID 20525402, 2010). "Interestingly, susceptibility to tuberculosis in an African cohort has been associated with a separate SNP cluster 3’ of the IL12B locus and of the neighbouring UBLCP1 gene." (PMID 28263993, 2017). "The “MAPK Signaling Pathway” includes genes like MAP3K2, PLA2G4A, and NFKB1, Lastly, the “Tuberculosis” pathway involves IFNGR2, ITGB2, and IL12B." (PMID 40621499, 2025).
lung carcinoma (4 papers, 2018 to 2024). "Furthermore, we isolated F4/80+ TAMs from PBS- or HCQ-treated mice with orthotopic lung cancer, and we found that the M1-like molecules (Nos2, Ifng, IL12b,and IL1b) were up-regulated and the M2-like molecules (Arg1, Tgfb1, IL10, and Ido1) were down-regulated with HCQ treatment." (PMID 30373678, 2018).
multiple sclerosis (4 papers, 2018 to 2025). A progressive autoimmune disorder affecting the central nervous system resulting in demyelination. "Overall, patients with PMS had lower levels of IL-12B and its related cytokines, suggesting that acute inflammation is less prevalent in this course of multiple sclerosis." (PMID 36756308, 2023). "CCL3, IL-12B, CXCL10 and IL-8 discriminated between multiple sclerosis patients and controls, but only IL-12B differed between patients with relapsing-remitting and progressive multiple sclerosis." (PMID 36756308, 2023). "Through sophisticated analyses, we identified four cytokines with limited association with each other, that discriminated between patients with multiple sclerosis and healthy controls, namely, CCL3, IL-12B, CXCL10 and IL-8." (PMID 36756308, 2023).
parasitemia (4 papers, 2012 to 2023). "Our data revealed that carriage of AA (P = 0.0001) and AC (P = 0.01) genotypes of IL12B 3′UTR polymorphism was associated with a significant increase of mean log-parasitemia relative to rare homozygous genotype CC." (PMID 23071570, 2012). "Remarkably, they specifically up-regulated HLA-DR,DP,DQ in response to parasite infection and up-regulated IL-12b mRNA more vigorously than cells from seronegative humans." (PMID 31316920, 2019). "IL4, IL12B, LTA, NCR3 have either been linked to mild malaria or parasitemia, alleles in these genes have been associated with these phenotypes." (PMID 25887595, 2015). "In a family-based study from Burkina Faso, significant interactions impacting on parasitemia levels were identified involving HBB variant HbC and LTA + 80 or IL12B polymorphisms." (PMID 25887595, 2015). "Here we extend this analysis by investigating genetic association between polymorphic variability of IL12B, which encodes the IL-12p40 subunit of IL12, with blood parasitemia." (PMID 23071570, 2012). "Box-plot diagrams displayed a gradual decline in parasitemia across three genotypes of IL12B+1188 locus in which AA, AC and CC had the highest, intermediate and lowest median values respectively." (PMID 23071570, 2012). "Genetic association of IL12B promoter and 3′UTR polymorphisms with parasitemia at genotypic level." (PMID 23071570, 2012).
Chagas disease (3 papers, 2014 to 2020). A parasitic infection caused by Trypanosoma cruzi. "Another study determined the role of genetic polymorphism in the IL-12, and it was the C allele of IL-12B 3′UTR that acted as a risk factor and influenced the susceptibility to develop cardiomyopathy in Chagas disease." (PMID 24608170, 2014). "The present study was designed to determine whether SNPs in IL12B, IL10, IFNG and IL4, key genes involved in the promotion and control of Th1 differentiation and IFN-g production to T. cruzi, are associated with Chagas disease outcome." (PMID 32733459, 2020).
hepatocellular carcinoma (3 papers, 2017 to 2025). A malignant tumor that arises from hepatocytes. "Their pooled data showed a significant association between IL-12B rs3212227 polymorphisms and overall cancer risk, especially in hepatocellular carcinoma, nasopharyngeal cancer, and among Asians." (PMID 32458622, 2020). "We observed a significant association between IL-12B rs3212227 and overall cancer risk, especially in hepatocellular carcinoma, nasopharyngeal cancer, and among Asians." (PMID 28415696, 2017).
Hypertension (3 papers, 2019 to 2021). The presence of chronic increased pressure in the systemic arterial system. "IL-12 polymorphism is closely related to the incidence of hypertension-induced complications: hypertension patients who carry the IL12B 1159 A/A genotype exhibit a lower risk of incidence of stroke, while IL12B A/A carriers have an elevated risk of stroke." (PMID 32194399, 2020). "In the dominant model, we did not observe significant associations between IL12B rs6871626 and AR or hypertension, although the incidence tended to be higher in risk genotypes of IL12B rs6872626." (PMID 34211061, 2021). "In addition, we detected for the first time an association between IL12B rs6871626 and hypertension in TAK, which was not attributed to renal artery involvement." (PMID 34211061, 2021).
Listeria infection (3 papers, 2015 to 2023). "Indeed, MHV68 infection did not enhance the transcription of Tnf, and only marginally enhanced the transcription of Il6 and Il12b even in control mice following Listeria infection, and did not rescue the defect in Tnf and Il6 induction observed in HOIL-1 KO mice." (PMID 25599590, 2015).
ovarian carcinoma (3 papers, 2016 to 2018). A malignant neoplasm originating from the surface ovarian epithelium. "A hallmark of TAMs in ovarian cancer ascites is their defect to release IL-12 in response to inflammatory stimuli, which results from a transcriptional block of the IL12B gene encoding the p40 subunit." (PMID 28327095, 2017).